MRPS31P2 (mitochondrial ribosomal protein S31 pseudogene 2)
Gene: Unprocessed pseudogene on chromosome 13 (19,552,571 to 19,570,288, reverse strand). Ensembl gene ENSG00000232894.
Diseases named in the same sentence as MRPS31P2 in open-access papers:
MRPS31P2 is named in the same sentence as 2 diseases in open-access papers, as found by Europe PMC text mining. Sharing a sentence is not in itself a finding about the gene and the disease. The quoted sentences say what the papers report.
breast carcinoma (1 paper, 2025). "Our database identified well-known fusion genes that are commonly associated with breast cancer, such as ESR1::CCDC170, and revealed previously unreported fusion genes, including TPTE2::MRPS31P2 and LHFPL5::CLPSL1." (PMID 41213951, 2025). "The most frequently occurring fusion genes in each subtype were TTC6::MIPOL1 in HR+/HER2‒ breast cancers, LHFPL5::CLPSL1 in triple-negative breast cancer (TNBC), and TPTE2::MRPS31P2 in HER2+ breast cancers." (PMID 41213951, 2025).
MRPS31P2 also shares sentences with these, for which no sentence is quoted: triple-negative breast carcinoma (1 paper).